HNF4A (hepatocyte nuclear factor 4 alpha)
Diseases named in the same sentence as HNF4A in open-access papers (continued):
Sharing a sentence is not in itself a finding about the gene and the disease.
tumor (continued). "(G–H) ChIP-qPCR showing enrichment of HNF4α (G) and p-S133-CREB1 (H) at Ctnnb1 promoter in native colon tissues of WT (n= 3) mice, tumor tissues of ApcMin/+ (n= 3) mice, and Ctnnb1Δi.enh;ApcMin/+ (n= 3) mice." (PMID 39320349, 2024). "In the ASCL1 tumor subtype, there was a notable enrichment of transcription factors coactivated by PGC-1α, including HNF4A and PPPARA, which were among the top 10 most significantly enriched." (PMID 39589879, 2024). "Depletion of HNF4A-liver-TEs and KDM1A knockdown exerted notable suppressive effects on tumor cell growth, consistent with the observed effects in conventional HCC cell lines." (PMID 38965210, 2024). "Related transcription factors such as HNF4α and HNF1 are expected to be future targets for tumor treatment." (PMID 38993564, 2024). "Again, the tumours were proven to be HCC by H&E staining and immunostaining for CK19, GS, and HNF4α." (PMID 37752418, 2023). "HNF4α+ cells were found throughout the tumour, while CK19+ cells were found outside the tumour, indicating that the tumour originated from hepatocytes." (PMID 37752418, 2023). "We compared HNF4A and HNF4G expressions between normal human colon and tumor tissues in the TCGA and Skrzypczak datasets." (PMID 37309673, 2023). "Knocking down HNF4α in hepatocellular carcinoma impairs SAA metabolism, increases tumor cell tolerance to Met deprivation and sorafenib, and promotes tumor EMT." (PMID 37699892, 2023). "Both HNF4A and HNF4G were reduced in tumor tissue from both datasets, mirroring reduced BTNL3 and BTNL8 expressions in human tumors." (PMID 37309673, 2023). "We also observed increased motif accessibility for the hepatocyte nuclear factors (HNF4A and HNF4G) in the Epi-H tumor clusters." (PMID 36973268, 2023). "For HNF4α-based targeting therapeutics in HCC, HNF4α and HNF1α have been used to inhibit HCC cell proliferation and eliminate tumor-specific features." (PMID 36249028, 2022). "All differentiation markers (CYP3A4, HNF4α and albumin) in infigratinib‐treated FGFR‐dependent tumours were significantly increased compared with their levels in vehicle‐treated tumours." (PMID 33179425, 2021). "Tumour sections were stained for markers of hepatocyte differentiation, such as CYP3A4, HNF4α and albumin." (PMID 33179425, 2021). "Since miR-134 targets and inactivates KRAS, Nanog mRNA, HNF4α, EGFR, ITGB1, and FOXM1, it also inhibits tumor invasion and metastasis." (PMID 33331954, 2021). "Downregulation of HNF4α in HCC results in upregulation of lnc‐APUE, leading to enhanced E2F1 expression and in turn accelerating G1/S transition and tumor growth." (PMID 33854885, 2021). "Infigratinib‐treated tumours showed higher expression of the differentiation markers CYP3A4, HNF4α and albumin, indicating a reduction in stemness." (PMID 33179425, 2021). "DW14800 has an anti-tumor effect in HCC, for it can increase the expression of HNF4α by reducing the level of H4R3me2s and enhancing the transcription of HNF4α." (PMID 34513846, 2021). "Additional studies to investigate the interaction between HNF4α and CBS will therefore help to better understand the complex role of CBS in tumor biology." (PMID 32770044, 2020). "We observed already statistically significant different accessibilities between healthy controls and COAD samples for TFs HNF4A and DLX2 and the other TFs, GRHL2, EVX2, LYL1, and PU.1 showed statistically significant differences at a 1% tumor level." (PMID 31604930, 2019). "Both these genes exhibit multiple regions of increased chromatin accessibility in both tumor tissue and OE19 cells, several of which contain motifs for HNF4A or GATA6 binding." (PMID 30962179, 2019). "Next, we compared accessibilities in subsamples with different tumor fractions for TFs selected based on our previous ATAC-seq and nucleosome plasma mapping, i.e., GRHL2, EVX2, DLX2, HNF4A, LYL1, and PU.1." (PMID 31604930, 2019). "Moreover, the KO of Hnf4a suggested that Hnf4a could act as tumor suppressor in liver." (PMID 29899848, 2018).
tumor (continued). "The result illustrated that BBR and knockdown of HNF4α suppressed tumor growth in vivo, and BBR decreased HNF4α, WNT5A and cytoplasmic β-catenin levels, the same effect as HNF4α knockout in vivo." (PMID 30405404, 2018). "At least for HNF4α-positive HCC, these data reveal the therapeutic potential of targeting the circadian clock in tumor progression." (PMID 30341289, 2018). "The study also identified MYC, HNF4A and TGFB1 as top upstream regulators correlating to tumor tissue content." (PMID 28445515, 2017). "Thus, HNF-4α could be considered as a potential tumour suppressor in liver cells." (PMID 28643803, 2017). "Our results in primary human tumours are supported by recent findings in the mouse small intestine, where CDX2 has been found to regulate HNF4α occupancy to control intestinal gene expression." (PMID 27677335, 2016). "Our results showing coordinate induction of HMGA2, TGF-β along with the EMT markers are consistent with the model that viral non-coding RNA targeted depletion of HNF4α sets the stage for the development of HCC, tumor invasion and metastasis." (PMID 26157476, 2015). "Forced HNF4α expression in dedifferentiated and aggressive HCC is sufficient to reduce tumor cell motility/invasivity by inducing differentiation and EMT inhibition." (PMID 28943628, 2015). "Quantitative assessment of HNF4α protein in HCV-infected liver tumors was made from similar Western blot analyses of seven controls and eight tumor tissues from human hepatocyte-engrafted and HCV-infected MUP-uPA/SCID/Bg mice." (PMID 26157476, 2015). "Another target for miR-34a is hepatocyte nuclear factor 4 alpha (HNF4A), a tumor suppressor in hepatocytes." (PMID 26287733, 2015). "Restoration of TCF2 expression induced expression of HNF4α, a transcriptional target of HNF1β, indicating that epigenetic silencing of TCF2 leads to alteration of the hepatocyte nuclear factor network in tumours." (PMID 16479257, 2006). "In contrast, almost half of the cases in the non-mucinous group were double-positive for TTF-1 and HNF4α (7/15, 46.7%), and their expression patterns were heterogenous and mutually exclusive within the same tumor (Online Resource 5a)." (PMID 38710944, 2025). "We first asked whether the relationship among ATRX, HNF4A, CDX2 and LY6D expression identified in our mouse model exists in human tumour samples." (PMID 40468074, 2025). "Despite this reduction, the remaining tumors were still panCK+ but HNF4A−, indicating that Sall4 deletion does not alter tumor cell fate but inhibits CCA tumor expansion." (PMID 40932240, 2025). "Moreover, consistent with a role for ATRX, HNF4A and CDX2 in maintaining lineage fidelity and suppressing squamous-like plasticity, we observed low expression of these proteins in tumours containing LY6D+ cells." (PMID 40468074, 2025). "Overall, we confirmed the existence of two distinct tumor subpopulations expressing either HNF4A or LEF1 and found that these two markers could distinguish tumor subpopulations better than β-catenin staining alone." (PMID 39567475, 2024). "In addition, consistent with tumor tissue stainings, HNF4A and LEF1 marked fetal and embryonal tumor organoids, respectively." (PMID 39567475, 2024).
tumor (continued). "The absence of HNF4A in the embryonal tumor subset is intriguing because HNF4A is generally considered a central regulator of hepatic differentiation and essential for maintaining liver function." (PMID 39567475, 2024). "Furthermore, we demonstrated a mutually exclusive expression pattern of HNF4A and LEF1 in a cohort of tumor tissues by IF staining." (PMID 39567475, 2024). "In addition, the dichotomous expression pattern of the transcription factors HNF4A and LEF1 allows for a clear distinction between the fetal and embryonal tumor cells." (PMID 39567475, 2024). "Users can select specific datasets (e.g., GSE14520) and generate scatter plots to reflect the correlation between SLC215A15 and HNF4A in tumor or nontumor samples." (PMID 37635767, 2023). "A clue to understanding this duality is the presence of a target gene for Wnt/β-catenin signaling (Hepatocyte nuclear factor 4 alpha (HNF4α)), as well as Forkhead box protein M1 (FOXM1), which influences Wnt/β-catenin signaling and is involved in tumor malignancy." (PMID 37046727, 2023). "This picture differs from tumors induced by myr-AKT/YAPS127A, which stained positive for CK19 in most tumor regions (but were negative for nuclear HNF4α)." (PMID 37381005, 2023). "To determine whether the restoration of HNF4A, HNF4G, and Btnl1 expression in tumors from VA;Bcl9F/F;Bcl9lF/F mice affected tumor-infiltrating γδ T cells, we quantified these cells in tumor tissue." (PMID 37309673, 2023). "In HNF4α-positive HCC, the increase in BMAL1 expression slows tumor growth in vivo, thus indicating that BMAL1 may be a potential target for reversing HNF4α-positive HCC." (PMID 36647780, 2023). "In the tumor “top100” list, TAF1 and HNF4A are the main hub genes." (PMID 35428183, 2022). "Regarding tumor development it should be noted that E-cadherin is able to inhibit Nrf2 activity and HNF4α can block β-catenin activity, explaining partial differentiation of HLN cells; a phenomenon known from many blastemal human tumor (in particular following chemotherapy)." (PMID 36209041, 2022). "A consistent tissue specificity of HNF4A was observed in this cohort as well, and we found no systematic differential expression of HNF4A between the tumor and matched normal tissues." (PMID 35227282, 2022). "In addition, Lysine Demethylase 8(KDM8) is a potential tumor suppressor downregulated in HCC and is a downstream target of HNF4α signaling." (PMID 36249028, 2022). "It was predicted that the genes such as FOXM1 and MYBL2 were activated while HNF4A and PPARGC1A were inhibited in tumor cells, which drove liver tumor, digestive organ tumor, abdominal neoplasm, tumorigenesis of tissue, neoplasia of cells and oxidation of lipid." (PMID 36212481, 2022). "In addition, multiple hepatocyte nuclear factors (e.g., HNF1A, HNF4A, and HNF4G) we identified in tumor cells have been shown to be specific for proximal tubule cells, which are the original cells of ccRCC79." (PMID 35853872, 2022). "Interestingly, staining of both HNF4α and CK-19 in MAPEpo tumors with a clear boundary confirmed a combined HCC and ICC within the same tumor." (PMID 36494846, 2022). "Remaining tumor tissues, which were mainly located on tumor rims next to normal tissues, were found to highly express the hepatic nuclear marker HNF4α, suggesting restoration of hepatocyte's identity." (PMID 35343115, 2022). "Xenograft tumor of HCT 116 showed an increased expression of neuronal genes MAP2 and SYN1, neural stemness genes CDH2, MSI1, NCAM1, SOX2/9, VIM and ZEB2, and genes for mesodermal and endodermal tissues (ACP5, AFP, DESMIN, HNF4A and KRT8)." (PMID 33468253, 2021). "Therefore, in cooperation with microRNAs, HNF4α inhibits the activation and degradation of SNAIL via NF-κB by downregulating the expression of RELA, thereby blocking the EMT process in tumor cells and alleviating or reversing the pathology of cancer." (PMID 33462379, 2021).
tumor (continued). "The malignant degree of the tumor correlated negatively with the expression level of HNF4a, which suggests that HNF4a plays an important negative role in the development of BLCA." (PMID 33628089, 2021). "Tumour tissues were then subjected to immunohistochemistry to assess cell differentiation, as indicated by the cytoplasmic‐to‐nuclear ratio and markers such as CYP3A4, HNF4α and albumin." (PMID 33179425, 2021). "The tumor cells strongly expressed CK19 (bile duct epithelial cell marker) but not HNF4α (hepatocyte markers), and they lacked tubular structures, indicating that the tumor was a poorly differentiated iCCA." (PMID 34667161, 2021). "In tumor cells, HNF4α downregulation leads to lnc‐APUE upregulation, which prevents the inhibition of miR‐20b on E2F1 expression and thereby promotes cell cycle progression and tumor growth." (PMID 33854885, 2021). "Interestingly, upregulation of the LINC00858/HNF4α axis, in turn, leads to downregulation of WNK2, which acts as tumor-promoting mechanism." (PMID 34771521, 2021). "It is shown that HNF4α does not act as a tumor suppressor but can promote intestinal tumorigenesis in the APCMin mouse model of intestinal carcinoma via its direct regulation of oxidoreductase-related genes and reactive oxygen species production." (PMID 31695151, 2020). "Double immunostaining revealed that A6+/Hnf4α+ cells were present within the tumor section, but not observed either in tissues adjacent to tumors or in control livers." (PMID 32372053, 2020). "HNF4A, a tumor suppressor in the liver, thus may act as an inhibitor of ERK-phosphorylation-mediated tumor development." (PMID 33198372, 2020). "HNF4α is also an effective circadian tumor suppressor, in particular its main isoform expressed in the adult liver (P1-HNF4α), whereas a different promoter driven isoform (P2-HNF4α) suppresses ARNTL and is expressed in HNF4α-positive HCC." (PMID 31718031, 2019). "The expression change of HNF4α might be positively correlated with E-cadherin, and negatively with MMP9 in IL-23 mediated tumor progression." (PMID 29983862, 2018). "While HNF4α and BMAL1 are robustly co-expressed in normal hepatocytes, of significance is the distinct downregulation of BMAL1, which has been demonstrated to play tumor suppressive roles in HNF4α-positive HCC." (PMID 30341289, 2018). "HNF4α was low, confirming that the tumor samples were not contaminated with significant levels of hepatocytes." (PMID 27280413, 2016). "In addition, low ASK1 and HNF4α expression were more likely in human HCC specimens containing high levels of AFP, tumor diameter > 5 cm and advanced tumor stage, vice versa." (PMID 27050273, 2016). "Furthermore, its inhibition in cells from advanced HCC restores hepatocyte differentiation inducing the up-regulation of master factors (i.e., HNF4α/FOXA1/FOXA3) and leading to tumor regression." (PMID 28943628, 2015). "We show depletion of HNF4α in liver tumors of HCV-infected humanized mice by HCV derived small non-coding RNA (vmr11) and resultant induction of EMT genes, which are critical determinants of tumor progression." (PMID 26157476, 2015). "On the other hand, the co-expression of HNF4A and its metabolic gene targets is markedly different in normal and tumor samples." (PMID 25961905, 2015). "Similarly to HNF4α, indeed, these proteins are down-regulated in HCC and their overexpression in tumor cell lines was found to suppress EMT and invasion." (PMID 28943628, 2015). "HNF4A interacts with proteins that are little characterised such as ACSS3, BDH1 and FDXR, and highlights the need for further functional investigations of these proteins in tumour pathogenesis." (PMID 24728830, 2014). "Moreover, restoration of TCF2 expression induced expression of HNF4α, a transcriptional target of HNF1β, indicating that epigenetic silencing of TCF2 leads to alteration of the hepatocyte nuclear factor network in tumours." (PMID 16479257, 2006).
tumor (continued). "Notably, recent findings indicate that AMPK activity status governs the dual functionality of HNF4A in HCC, shifting it from a tumor suppressor under low AMPK activity to a tumor promoter under high activity, thereby linking metabolic sensing to phenotypic plasticity." (PMID 40818043, 2026). "HCCOs derived from end-stage tumours of cohort 5 (BM) mice expressed β-catenin, its downstream target GS and retained MYC overexpression as well as markers of proliferation (Ki-67) and differentiation (HNF4a), features that are shared with the corresponding primary tumour." (PMID 39972137, 2025). "HNF4α exerts an inhibitory effect on EMT through its effect on the Wnt/β-catenin signaling pathway via the upregulation of E-cadherin, along with the downregulation of β-catenin and Vimentin, which collectively contribute to the suppression of tumor growth and metastasis in HCC." (PMID 40277924, 2025). "Hence, understanding HNF4α’s role in NKX2-1-positive LUAD and its molecular relationship with NKX2-1 could greatly help characterize lineage plasticity and tumor progression in LUAD." (PMID 40707360, 2025). "Therefore, TAF1 is a hub gene in both the normal and tumor lists, while HNF4A, MAX, and MYC are not." (PMID 35428183, 2022). "Some of these molecular alterations found in squamous PDAC, such as inhibition of pancreatic epithelial differentiation genes (HNF4A and GATA6) together with increased hypoxia, HIF1A, C-MYC and WNT, insulin, and PI3K-AKT signaling, promote a metabolic rewiring of tumor cells to glycolysis." (PMID 34503261, 2021). "Taken together, downregulation of HNF4α may lead to the upregulation of lnc‐APUE, and lnc‐APUE may work as a miR‐20b sponge to prevent the miR‐20b‐mediated repression on E2F1 expression, thereby promoting G1/S transition and tumor growth." (PMID 33854885, 2021). "HNF4A is regulated by AMPKα signalling and resides upstream of WNT signalling via WNT5A, whose knockdown activity results in cell cycle arrest, cyclin down‐regulation and tumour growth inhibition, findings of which were all consistent the results of the current study." (PMID 34309216, 2021). "By contrast, SHP and HNF4α expression was low or absent in most tumours." (PMID 26280373, 2015). "In tumor cells, HNF4α downregulation leads to lnc‐APUE upregulation, which may work as a miR‐20b sponge to prevent the miR‐20b‐mediated repression on E2F1 expression, resulting in increase of E2F1 level and in turn acceleration of G1/S transition and tumor growth." (PMID 33854885, 2021). "Our research still could not answer how HNF4α participates in tumor progression." (PMID 29983862, 2018). "However, a drug targeting that protein failed to impact tumor cell survival, and may have demonstrated a role for HNF4A as a tumor suppressor." (PMID 22848702, 2012). "As expected, all tumor iCCA lesions in both cohorts were positive for p-AKT and the biliary epithelial marker CK19 and negative for the HNF4α hepatocyte marker." (PMID 38909034, 2024). "Conversely, the embryonal tumor organoids showed LEF1 expression broadly, with HNF4A largely absent." (PMID 39567475, 2024). "In most HCC datasets, both in tumor and nontumor tissues, SLC25A15 and HNF4A are significantly positively correlated." (PMID 37635767, 2023). "In tumor cells, ACSM3 mRNA was upregulated by HNF4α, downregulated by PPAR-γ, there was a negative feedback loop between ACSM3 and AKT, and ACSM3 expression correlated with fatty acid beta oxidation." (PMID 33923085, 2021). "Two major transcriptional regulators, the hepatocyte nuclear factor 4, alpha (HNF4A) and ubiquitin C (UBC) genes, had no predictive expression value in HCC-R tumor tissues." (PMID 24377043, 2013). "Rather than promoting tumor formation, Sall4 overexpression led to an expansion of an intermediate LPC-like cell population, characterized by persistent lipid accumulation and dual HNF4A-panCK expression." (PMID 40932240, 2025).